Y_RNA (Y RNA )
Gene: Miscellaneous RNA gene on chromosome 3 (125,516,979 to 125,517,086, forward strand). Ensembl gene ENSG00000201800.
Homologues: Orthologues: chimpanzee Y_RNA (96% identical), macaque Y_RNA (94% identical). Paralogues in human: RNY1 (87% identical), Y_RNA (87% identical), Y_RNA (86% identical), Y_RNA (85% identical), RNY1P11 (84% identical), Y_RNA (84% identical), Y_RNA (83% identical), Y_RNA (82% identical), RNY1P10 (81% identical), RNY1P12 (81% identical), RNY1P15 (81% identical), RNY1P8 (81% identical), and 94 more.